CNTN1 (contactin 1)
Diseases named in the same sentence as CNTN1 in open-access papers (continued):
Sharing a sentence is not in itself a finding about the gene and the disease.
lung carcinoma (continued). "Following the discovery of CNTN1′s oncogenic role in lung cancer, it has become increasingly clear that its role in the induction of invasion and metastasis may be a shared commonality in other cancers as well." (PMID 32752094, 2020). "Understanding the role of CNTN1 in lung cancer ranges from tumor progression to treatment." (PMID 33194679, 2020). "Thus, aberrant expression of CNTN1 promote survival and growth of malignancies including lung cancer, gastric cancer and/or squamous carcinoma." (PMID 29673312, 2018). "This is consistent with the published incidence for CNTN-1+ versus CNTN-1− primary lung carcinomas." (PMID 23724143, 2013). "Furthermore, in our study of 63 primary lung cancers, we observed 65% of primary lung cancers being contactin-1 positive and in these carcinomas, 61% were E-cadherin negative." (PMID 23724143, 2013). "Lung cancer patients with high levels of CNTN-1 have poor prognosis." (PMID 23724143, 2013). "CNTN-1 plays a critical role in the metastasis of A549 lung cancer cells." (PMID 23724143, 2013). "In primary lung carcinoma, high levels of CNTN-1 co-existed with low levels of E-cadherin." (PMID 23724143, 2013). "Additionally, in our analysis of 46 stages I/II and 17 stages III/IV primary lung carcinomas, approximately 61% of stages I/II and 76% of stages III/IV carcinomas are CNTN-1-positive, indicating a role of CNTN-1 in lung cancer progression." (PMID 23724143, 2013). "CNTN1 is known to mediate cell surface interactions in the development of the nervous system by signaling between axons and myelinating glial cells and has been shown to promote cellular adhesion and invasion of lung cancer cells." (PMID 19737398, 2009). "Apart from the PI3K/AKT pathway, CNTN1 is also associated with the RhoA pathway in gastric cancer; VEGF-C/VEGFR-3 pathway in lung, gastric, and esophageal cancers, and OSCC; α7 nAChR/ERK and Src-p38 MAPK-C/EBPα pathways in lung cancer; and Notch1 and RET/PTC3 pathways in thyroid cancer." (PMID 33194679, 2020). "In lung cancer cells, NNK directly increased the expression of CNTN1, at both the transcriptional and translational levels and activated α7 nAChR downstream to the AKT and ERK pathways." (PMID 33194679, 2020). "The prognostic value related to the worse prognosis of IL-8, SCG2, NCAM1, CNTN1, CADM1, NPTX1, and APOD tumor transcripts were evaluated in seven lung cancer transcriptome datasets (validation set)." (PMID 31455042, 2019). "Approximately 65% (41/63) and 35% (22/63) of primary lung carcinomas expressed readily detectable (CNTN-1+) and undetectable CNTN-1 (CNTN-1−), respectively by IHC." (PMID 23724143, 2013). "To further investigate CNTN-1-mediated oncogenesis, we have knocked-down CNTN-1 in A549 lung cancer cells." (PMID 23724143, 2013). "This indicated that NNK promoted lung cancer progression by upregulating CNTN1 expression via the α7 nAChR/ERK pathway but not the α7 nAChR/AKT pathway." (PMID 33194679, 2020). "CNTN1 was discovered as an immediate downstream effector of the vascular endothelial growth factor (VEGF)C-VEFGR3/Flt4 that induced invasion and metastasis in lung cancer via the Src/p38 MAPK-mediated C/EBP signaling pathway." (PMID 32752094, 2020). "The inhibition of the AKT pathway in drug-resistant lung cancer cells using LY294002 conferred the same result without influencing CNTN1 expression." (PMID 33194679, 2020). "In addition, CNTN-1-mediated metastasis is regulated by VEGF-C and CNTN-1 enhances GTP-bound RhoA which is attributable to CNTN-1-promoted lung cancer invasion and metastasis." (PMID 23724143, 2013). "Suppression of CNTN1 expression abolished the ability of lung cancer cells to invade and metastasize by activating RhoA, but not Cdc42 or Rac1, suggesting that CNTN1 is a key regulator of invasion and metastasis in lung adenocarcinoma." (PMID 22580838, 2012).
lung carcinoma (continued). "Furthermore, knockdown of CNTN1 in lung cancer cells decreased the expression of SIP1 and Slug but not Snail, which is the most studied E-cadherin transcription inhibitor." (PMID 33194679, 2020). "In supporting this suggestion, while CNTN-1 negative lung cancer regions could be E-cadherin positive, from the same patient the CNTN-1 positive lung carcinomas expression reduced levels of E-cadherin." (PMID 23724143, 2013). "Based on these evidences, CNTN-1 mediated regulation of E-cadherin and AKT is not restricted to lung cancer and may play a role in other cancers expressing CNTN-1." (PMID 23724143, 2013).
nephrotic syndrome (13 papers, 2018 to 2026). A collection of symptoms that include severe edema, proteinuria, and hypoalbuminemia; it is indicative of renal dysfunction. "This study identifies CNTN1 antibodies as the pathological link between immune-mediated neuropathies and nephrotic syndrome caused by MGN, providing a mechanistic explanation for numerous previous clinical observations." (PMID 36893151, 2023). "Patients with anti-CNTN1 can show high proteinuria levels as nephrotic syndrome is frequently associated." (PMID 36672019, 2022). "Patients with autoimmune neuropathy that is CNTN1-associated have an increased prevalence of nephrotic syndrome, which is often found to be due to MN." (PMID 34899763, 2021). "Although high prevalence of nephrotic syndrome in autoimmune nodopathies associated with anti‐CNTN1 IgG4, anti‐pan‐neurofascin IgG1, or anti‐NF186 IgG has increasingly been emphasized, routine urinalysis, which can be performed at every hospital, is not recommended in the diagnostic guidelines." (PMID 38980226, 2024). "Although CNTN1 is expressed by podocytes in normal kidney and is the target of anti-CNTN1 IgG4 in patients with nephrotic syndrome, it remains unknown whether the pathogenic mechanism in membranous nephropathy results from a function blocking, antigen-crosslinking or immune-complex deposition." (PMID 36999029, 2023). "The patient was ultimately diagnosed with anti-CNTN1 antibody-positive AN coexisting with Sjögren's disease and nephrotic syndrome." (PMID 42245643, 2026). "Anti‐CNTN1 IgG4‐positive autoimmune nodopathy concurrent with nephrotic syndrome: Our patients and a literature search." (PMID 38980226, 2024). "In contrast, nephrotic syndrome frequently co‐occurred with autoimmune nodopathies in patients harboring autoantibodies targeting nodal and paranodal proteins, especially CNTN1 (up to 8/10, 80%)." (PMID 38980226, 2024). "Patients who present with nephrotic syndrome should be tested for anti‐CNTN1 IgG4 antibodies, and patients who exhibit mild proteinuria should be tested for anti‐NF155 IgG4 antibodies." (PMID 38980226, 2024). "Membranous nephropathy was histologically identified in 15 patients who had both nephrotic syndrome and anti‐CNTN1 IgG antibodies." (PMID 38980226, 2024). "Ten patients (2.1% of the total cohort and 27.8% of the seropositive group) were monospecific for CNTN1 antibodies, and eight of these additionally had nephrotic syndrome." (PMID 36893151, 2023). "Histopathological characteristics of IgG4-RLD were investigated in a kidney biopsy of one CIDP patient (male, 54 years) with CNTN1/Caspr1-complex autoantibodies, nephrotic syndrome and microhematuria." (PMID 35095860, 2021). "This link has recently culminated in identifying CNTN1 as the main antigen involved in nephrotic syndrome in those with demyelinating neuropathy." (PMID 34899763, 2021). "Subsequently, a further seven patients with CNTN1 antibodies, an immune-mediated neuropathy, and confirmed nephrotic syndrome or suspected nephrotic syndrome with MGN confirmed on biopsy, were retrospectively identified from international collaborating centres." (PMID 36893151, 2023). "The majority of patients with CNTN1 antibodies presented with a neuro-renal syndrome characterised by a rapidly progressive, disabling, sensory-motor neuropathy accompanied by typical nephrotic syndrome, with oedema, low serum albumin, and elevated levels of urinary proteinuria." (PMID 36893151, 2023). "Besides paranodes, CNTN1 is also present on the surface of dorsal root ganglia and on podocytes, which may explain sensory ataxia and nephrotic syndrome, respectively." (PMID 36999029, 2023). "We identified 15 patients with immune-mediated neuropathy and concurrent nephrotic syndrome (biopsy proven MGN in 12/12), and 4 patients with isolated MGN from an idiopathic MGN cohort, all seropositive for IgG4 CNTN1 antibodies." (PMID 36893151, 2023).
nephrotic syndrome (continued). "Therefore, CNTN1 may represent a link between autoimmune neuropathy and nephrotic syndrome." (PMID 34899763, 2021). "One patient with anti-CNTN1 IgG3/IgG4 antibodies had a concurrent onset of CIDP and nephrotic syndrome because of membranous glomerulonephritis." (PMID 31753915, 2020). "Autoantibodies against paranodal/nodal molecules, such as CNTN1, NF186, and NF155, should be investigated in patients who present with nephrotic syndrome or mild proteinuria without symptoms." (PMID 38980226, 2024).
gastric cancer (12 papers, 2013 to 2025). A primary or metastatic malignant neoplasm involving the stomach. "CNTN1 expression was recently reported to be associated with lymphatic invasion and prognosis of gastric cancer." (PMID 29673312, 2018). "CNTN1 upregulation and its association with worse clinical features have been reported in breast cancer, astrocytic glioma, thyroid cancer, and stomach cancer." (PMID 33578925, 2021). "Association between CNTN-1 expression and clinicopathological features in gastric cancer indicated that CNTN-1 might contribute to the promotion of cancer cell metastasis in primary gastric cancer either." (PMID 23606831, 2013). "Several studies have clearly indicated CNTN1 as an independent prognostic factor in gastric cancer 87, 88)." (PMID 36389725, 2022). "CNTN1 upregulation was reported to correlate with worse clinical features in breast cancer, astrocytic glioma, thyroid cancer, and stomach cancer." (PMID 33578925, 2021). "In transgenic mice injected with gastric cancer or lung adenocarcinoma cells where CNTN1 was knocked down, the number of lung metastases and metastatic nodules was significantly smaller than that of the control." (PMID 33194679, 2020). "In vitro studies found that the knockdown of Flt4 in human MKN45 gastric cancer cells with short hairpin RNA directly downregulated CNTN1 expression, which validates the role of CNTN1 in the VEGFC-VEFGR3/Flt4 axis." (PMID 32752094, 2020). "In in vivo studies, the weight and volume of the tumors, obtained from transgenic mice injected with gastric cancer cells with a knocked down CNTN1 expression were almost identical to those from the control group." (PMID 33194679, 2020). "Recently, several reports revealed that CNTN1 is an important mediator of the progression of several cancers including lung adenocarcinoma, squamous carcinoma, hepatocellular carcinoma, and gastric cancer." (PMID 29673312, 2018). "In the preliminary study, we compared the specificity of antibody against CNTN-1 in gastric ulcer, chronic atrophic gastritis, and gastric cancer." (PMID 23606831, 2013). "The purpose of the present study was to investigate the presence of CNTN-1 in patients with primary gastric cancer using RT-PCR and Western Blot." (PMID 23606831, 2013). "High Contactin 1 expression correlates with poor prognosis in patients with gastric cancer." (PMID 41299419, 2025). "Moreover, CNTN-1 downregulation was recently reported to inhibit EMT progression in gastric cancer cells." (PMID 35711928, 2022). "Moreover, silencing of CNTN-1 expression was recently reported to decrease malignancy and improve the prognosis in patients with gastric cancer by inhibiting EMT progression." (PMID 35711928, 2022). "Moreover, ceRNA network identified hsa-miR-200c-3p as regulator of CNTN1 which further assert CNTN1 role in gastric cancer development via EMT." (PMID 36389725, 2022). "The knockdown of CNTN1 reduced cell migration and suppressed activation of RhoA and phosphorylation of p115 Rho guanine nucleotide exchange factor (RhoGEF, a RhoA activator) in gastric cancer." (PMID 33194679, 2020). "In the immunohistochemical analysis of specimens from gastric cancer, lung adenocarcinoma, primary OSCC, prostate cancer, and esophageal cancer, CNTN1 expression was significantly positively associated with lymphatic invasion, metastasis, late TNM stage, and a short overall survival time." (PMID 33194679, 2020). "F2 and CNTN1 has been reported to promote EMT in gastric cancer." (PMID 32309437, 2020). "Our data suggests that the detection of VEGF-C expression, CNTN-1 expression, lymphatic invasion, and serosa invasion may be a useful indicator of poorer prognosis in gastric cancer, respectively." (PMID 23606831, 2013). "This phenomenon may raise the possibility that intrinsic relationship of VEGF-C and CNTN-1 overexpression might play an important role in the lymphatic invasion in patients with gastric cancer." (PMID 23606831, 2013).
gastric cancer (continued). "VEGF-C, VEGFR-3, and CNTN-1 were widely expressed in the primary lesion of gastric cancer." (PMID 23606831, 2013). "Whether CNTN-1 expression has a positive correlation with lymphatic invasion and lymph node metastasis in gastric cancer is still unknown." (PMID 23606831, 2013). "We initially examined the expression of CNTN-1 mRNAs in gastric cancer by semiquantitative RT-PCR." (PMID 23606831, 2013). "These molecular characteristics were mainly driven by the eight NRGPI oncogenes (CYTL1, PLCL1, CNTN1, GRP, APOD, GPX3, FCN1, SERPINE1) as validated in the gastric cancer cell lines and clinical samples." (PMID 36389725, 2022). "In lung adenocarcinoma, gastric cancer, and OSCC, knockdown of CNTN1 strongly impaired cell migratory and invasive capacities in vitro without influencing proliferation." (PMID 33194679, 2020). "In a similar manner, significant correlation of CNTN1 expression with tumor size and TNM stage was also observed in stomach cancer." (PMID 32752094, 2020). "VEGF-C, VEGFR-3, and CNTN-1 expression was significantly correlated with the higher LVD values, respectively, indicating the grade of lymphangiogenesis in gastric cancer." (PMID 23606831, 2013). "The positivity rate of VEGF-C, VEGFR-3, and CNTN-1 in all cases with gastric cancer was 56.19%, 64.76%, and 58.09%, respectively, which was significantly higher than the positive rate of VEGF-C (17.14%), VEGFR-3 (15.23%), and CNTN-1 (21.90%) in control groups." (PMID 23606831, 2013). "An immunohistochemical analysis of 105 specimens showed that CNTN1 expression was 2.65 times more positive in primary gastric cancer patients than in the noncancerous control group, and it was almost exclusively observed in the cytoplasm of cancer cells." (PMID 33194679, 2020). "Our data suggest that CNTN-1 mRNA and CNTN-1 protein is highly expressed in gastric cancer compared to that in noncancerous gastric tissue." (PMID 23606831, 2013). "Moreover, CNTN1 promotes cell invasion, migration, and metastasis via the epithelial-mesenchymal transition (EMT) in gastric, lung, and prostate cancers and is defined as an independent prognostic predictor of gastric cancer." (PMID 33194679, 2020). "In a high-throughput analysis from The Cancer Genome Atlas (TCGA) database, CNTN1 was identified as one of six pivotal prognostic EMT-related genes (ERGs) to affiliate with pro-oncogenic pathways and show a significant prognostic value in gastric cancer through OS analysis." (PMID 32752094, 2020). "A comparative analysis between the mRNA and protein expression levels of CNTN1 and EMT-related proteins (E-cadherin, Snail, Slug, and N-cadherin) indicated that CNTN1 induced EMT by activating the transcription factor Slug but not Snail in gastric cancer cells." (PMID 33194679, 2020). "Knockdown of CNTN-1 results in the extensive inhibition of tumor metastasis and the improvement of survival in an animal model, but whether CNTN-1 contributes to the formation of lymphatic network and participates in the process of lymph node metastasis in gastric cancer has not been clarified." (PMID 23606831, 2013).
membranous nephropathy (11 papers, 2020 to 2026). "We present a 12-year-old boy with acute onset sensorimotor neuropathy and membranous glomerulonephritis associated with contactin-1 antibodies." (PMID 40607401, 2025). "In contrast, reports of patients with both autoimmune nodopathies and membranous nephropathy associated with autoantibodies targeting CNTN1 are increasing." (PMID 38980226, 2024). "Three of four (75%) patients who had anti‐CNTN1 antibodies showed severe proteinuria, two of whom were histologically diagnosed as having membranous nephropathy." (PMID 38980226, 2024). "Three of four (75%) patients with anti‐CNTN1 nodopathy had severe proteinuria, two of whom were histologically diagnosed as having membranous nephropathy." (PMID 38980226, 2024). "Clinical information was available for 21 patients who had anti‐CNTN1 nodopathy concurrent with membranous nephropathy." (PMID 38980226, 2024). "We also demonstrate a significant association between CNTN1 antibody titres and immunotherapy responsiveness in this neuro-renal syndrome, and establish CNTN1 as another new antigenic target in a small proportion of “idiopathic” membranous glomerulonephritis." (PMID 36893151, 2023). "The difference effect about low-dose rituximab between autoimmune nodopathy and membranous nephropathy, and the treatment regimen for nephrotic involvement in patients with anti-CNTN1 antibody need to be further explored." (PMID 35958552, 2022). "In fact, patients with anti-CNTN1 autoimmune nodopathy often had renal involvement with membranous nephropathy as granular deposits of IgG4 along the glomerular basement membrane in renal biopsies and the weakly expression of CNTN1 in the kidney." (PMID 35958552, 2022). "In membranous nephropathy, anti-CNTN1 antibodies may cross-react with CNTN1 expressed in podocytes, contributing to immune complex deposition and complement activation along the glomerular basement membrane." (PMID 40502862, 2025). "Recently, CNTN1 has been reported as a novel target antigen for membranous nephropathy." (PMID 39835101, 2024). "To date, CNTN1 has been recognized as a novel target in primary membranous nephropathy." (PMID 38980226, 2024). "Moreover, case series and case reports have shown a high incidence of membranous nephropathy in patients with anti‐CNTN1 nodopathy." (PMID 38980226, 2024). "However, rituximab was only used in a few anti-CNTN1-positive nodopathy patients with membranous nephropathy." (PMID 35958552, 2022). "Notably, 1 patient with anti-CNTN1 antibodies of IgG3 and IgG4 subclasses showed the contemporary occurrence of membranous glomerulonephritis." (PMID 31753915, 2020). "Except for leg edema (10/18, 56%), the clinical characteristics were indistinguishable from those of anti‐CNTN1 nodopathy without concurrent membranous nephropathy." (PMID 38980226, 2024).